INS (insulin)
Diseases named in the same sentence as INS in open-access papers (continued):
Sharing a sentence is not in itself a finding about the gene and the disease.
diabetes (continued). "Despite older adults with diabetes being most affected by and at risk of insulin errors in hospital, there has been limited in‐depth exploration of their experiences of insulin management during surgical hospital admissions and of their involvement in the development of insulin safety interventions." (PMID 41358572, 2025). "Some monogenic forms of diabetes can result from mutations in the INS gene." (PMID 40943666, 2025). "Vitamin D influences several pathways relevant to glycemic control; it regulates calcium homeostasis, which is important for insulin secretion, and it exerts antioxidant and immunomodulatory effects that could mitigate processes underlying diabetes." (PMID 40863099, 2025). "Moreover, the type of diabetes was also found to be significantly associated with knowledge of self‐administration of insulin." (PMID 40226177, 2025). "Diabetes is a metabolic disorder with multiple causes, characterized by chronic hyperglycemia and alterations in glucose, lipid, protein, and electrolyte metabolism due to defects in insulin secretion and/or action." (PMID 40217595, 2025). "The management of iatrogenic diabetes in this setting was previously addressed in a dedicated phase IV study that recommended the use of incretin-based drugs along with metformin, considering the underlying pathophysiology of pasireotide-related diabetes, with insulin reserved as a rescue measure." (PMID 41323967, 2025). "Therefore, there is a clear gap in the understanding of the trajectory of β-cell function and insulin sensitivity over time, particularly across the phases of menopause in women and the association with diabetes onset." (PMID 40361840, 2025). "Non-insulin-based indices and refined anthropometric markers may offer simpler risk stratification in prediabetes and diabetes." (PMID 41465784, 2025). "Nevertheless, there are still relatively few research examining how OSA affects insulin, pancreatic cells, and diabetes, and the underlying molecular process is still unknown." (PMID 41306568, 2025). "Similarly, TCF7L2 polymorphisms (rs12255372 and rs7903146) are among the strongest genetic risk factors for type 2 diabetes mellitus, influencing insulin secretion and glucose homeostasis." (PMID 40944253, 2025). "However, the multiple daily injection and basal insulin-only regimens showed different risk profiles for hospitalisation for known complications of diabetes." (PMID 39460755, 2025). "Notably, non-insulin-treated diabetes was more strongly associated with DCM than either insulin-treated diabetes or obesity alone." (PMID 41153651, 2025). "Furthermore, ROS-induced decreased insulin sensitivity is a crucial point in endothelial damage and cardiovascular problems associated with diabetes." (PMID 40225279, 2025). "The primary characteristic of diabetes is persistently elevated blood sugar levels, which are caused by a combination of lifestyle, environmental, and genetic factors that result in insulin resistance and issues with insulin production." (PMID 40574088, 2025). "In conclusion, this study provides novel longitudinal evidence of a statistically significant association between higher long-term insulin sensitivity, as assessed by Cum-eGDR, and a slower rate of frailty progression among middle-aged and older Chinese adults with diabetes." (PMID 41497955, 2025). "Diabetes is a modern-day challenge caused by a malfunction in insulin secretion from the pancreas." (PMID 40142957, 2025). "Androgens may exert an antagonistic effect on insulin action, leading to decreased insulin sensitivity and an elevated risk of developing diabetes." (PMID 41065315, 2025). "Another study showed that the conjugate ameliorated insulin-deficient diabetes in male mice to a greater extent than a single GLP-1 agonist, without causing feminizing effects, and upregulated anti-apoptotic pathways in cultured human islets produced by the monoagonists." (PMID 40299427, 2025).
diabetes (continued). "By demonstrating that LCD markedly reduces GV in insulin-deficient patients, our study highlights an additional therapeutic advantage of carbohydrate restriction beyond HbA1c reduction, underscoring its potential role in optimizing diabetes management." (PMID 41586239, 2025). "For COVID-19 patients with diabetes, insulin therapy has been associated with increased mortality, whereas metformin initially exhibited a therapeutic potential during the early stage of the pandemic, possibly due to its antiviral and anti-inflammatory properties." (PMID 40391966, 2025). "Moreover, a study suggests that a low-GI diet, such as one incorporating BGNF, can improve insulin sensitivity and reduce the risk of long-term complications in individuals with diabetes." (PMID 40026940, 2025). "Notably, age, knowledge level, prior receipt of diabetes-related information, and the sources of that information were significantly associated with insulin administration practices." (PMID 40471961, 2025). "We hypothesize that women with a predisposition to diabetes may face a higher risk of developing the disease due to increased insulin resistance from fat accumulation and inadequate β-cell compensation during the premenopausal phase." (PMID 40361840, 2025). "However, ER stress-induced β-cell dysfunction is a key contributor to the pathogenesis of insulin-deficient diabetes." (PMID 40076537, 2025). "Regarding the association between depression and patients’ clinical characteristics, a significant association was found between depression and type of diabetes therapy, with patients on insulin experiencing the highest percentage of mild to severe depression (77.4%, P-value = .011)." (PMID 40355242, 2025). "The pathogenesis of type 2 diabetes mellitus arises from inadequate insulin secretion caused by beta cell dysfunction, which often occurs alongside the onset of insulin resistance, ultimately causing the beta cells to be unable to compensate for the high insulin demand." (PMID 40471239, 2025). "However, in populations with diabetes, metabolic disorders caused by impaired insulin secretion from β-cells likely make any level of alcohol consumption a risk factor for liver cancer." (PMID 40944258, 2025). "By improving activation kinetics, this approach could offer a practical solution for reducing the risk of insulin-induced hypoglycaemia, advancing diabetes management." (PMID 40836936, 2025). "In the present study, we provide evidence that PDAC-associated diabetes is distinguished by a global downregulation of key islet hormones (INS, GCG) as well as β-cell-enriched transcription factors such as MAFA and PAX4, and hormone receptors such as GCGR, SSTR3 and SSTR5." (PMID 40244011, 2025). "Activity during the dark phase of the day (e.g., in shift workers, modern lifestyles) leads to an impaired insulin response to glucose and is most likely an important risk factor for the development of obesity, night eating syndrome, hypertension, diabetes, and cancer." (PMID 40650041, 2025). "However, excessive consumption, especially the high content of saturated fat, reduces β-cell function and insulin sensitivity while increasing the body mass index and increasing the risk of diabetes." (PMID 40219013, 2025). "Type 1 diabetes mellitus (T1D) is a chronic autoimmune disorder characterized by immune-mediated destruction of pancreatic β-cells, leading ultimately to an absolute insulin deficiency, and lifelong requirement of exogenous insulin." (PMID 41148826, 2025). "However, insulin initiation is often delayed, increasing the risk of diabetes-related complications." (PMID 39810242, 2025). "EE may contribute to a higher diabetes risk due to insulin resistance and reduced insulin secretion." (PMID 40608790, 2025). "Obesity-induced insulin resistance and physiological roles in insulin secretion and responses may partially explain the differential associations between diabetes and different cancer sites found in the present study." (PMID 40831756, 2025).
diabetes (continued). "However, metformin plus insulin or metformin plus sulfonylureas increased the risk of liver cancer in patients with diabetes‐associated MAFLD or MASLD." (PMID 39949980, 2025). "Previous research has suggested that FA (16:0) and FA (18:0) may impair insulin sensitivity, thereby increasing the risk of diabetes." (PMID 41373632, 2025). "Diabetes mellitus is a chronic metabolic disease caused by insufficient insulin secretion or insulin resistance, which is mainly characterized by abnormally high blood glucose levels, and according to the division, diabetes mellitus can be classified as type I, type II, gestational or other types." (PMID 40137284, 2025). "These individuals are particularly vulnerable to T2DM-related bone fragility due to additional factors, such as senile osteoporosis, severe VD deficiency, comorbidities, insulin use, and diabetes-related complications, particularly diabetic neuropathy and retinopathy, which predispose them to falls." (PMID 40313432, 2025). "Given the temporal proximity to pembrolizumab administration and the absence of alternative precipitating factors or newly introduced medications, the ICI was identified as the most likely etiological factor for the development of acute-onset insulin-deficient diabetes." (PMID 41018379, 2025). "It is generally believed that insulin users have a longer course of diabetes, which may be related to the long-term hyperglycemia causing swelling, degeneration and even necrosis of nerve fibers, leading to nerve demyelination, and then peripheral neuropathy." (PMID 40131908, 2025). "This may be linked to metabolic syndrome in patients with OA, characterized by obesity and insulin resistance, which can increase diabetes risk by affecting insulin secretion and action." (PMID 40802604, 2025). "Genetic studies have identified African ancestry-linked variants, such as ZRANB3, that impair insulin secretion and increase diabetes risk, reinforcing the critical role of the insulin secretory pathway, where defects can directly contribute to the development of diabetes." (PMID 41030733, 2025). "Despite these improvements, the mechanisms underlying the efficacy of insulin in diabetes remain unclear." (PMID 40299682, 2025). "Having to take insulin was associated with having severe diabetes and the “last resort” by many." (PMID 40171977, 2025). "The glucose-stimulated insulin secretion, mitochondrial functionality and energy metabolism of patients carried 3243 mutation was reduced significantly, increasing the risk of developing diabetes." (PMID 40862129, 2025). "While hypertension primarily affects vascular health and white matter integrity, diabetes has been associated with specific disruptions in glucose metabolism in memory-critical brain regions and altered insulin signaling pathways that play important roles in synaptic plasticity and memory formation." (PMID 40630402, 2025). "Additionally, the insulin signaling, glucagon signaling, and diabetes-related pathways also showed positive associations with 23-deoxycholic acid and estrone." (PMID 40731966, 2025). "Current studies have shown that with advancing age, there are many physiological mechanisms, such as insufficient insulin secretion, as well as increased insulin resistance caused by changes in body composition and sarcopenia, leading to a higher prevalence of diabetes in the old adults." (PMID 40806039, 2025). "The American Diabetes Association Standards of Medical Care in Diabetes (2020) also recommend SMBG for patients on non-insulin therapies who require adjustment of diet, physical activity, or medications, and CGM for individuals with type 2 diabetes who have not achieved glycemic targets." (PMID 41458677, 2025).
diabetes (continued). "A reduction in the risk of diabetes with significant improvements in glucose and insulin, both fasting and postprandial, HOMA-IR, weight, systolic blood pressure, and triglycerides were found in a 6-month intervention study with dieting and physical activity in PLWH and impaired fasting glucose." (PMID 40150513, 2025). "Diabetes is the result of chronic hyperglycemia caused by insulin dysregulation." (PMID 40565059, 2025). "EPAC1, is mainly involved in regulating endothelial permeability and vascular tone, as well as cell migration and adhesion while EPAC2 is more more closely linked to metabolic diseases such as diabetes due to its role in insulin secretion and glucose homeostasis." (PMID 40346550, 2025). "In the study, alloxan-induced diabetes was employed as a model, leading to pancreatic inflammation and the degeneration of Langerhans islet beta cells, ultimately causing hyperglycemia, reduced insulin production, and increased lipid levels." (PMID 40463898, 2025). "This article reviews the impact of mtDNA variants in diabetes, specifically with regards to the m.3243 A > G variant effects on mitochondrial function and insulin secretion and other mtDNA variants that contribute to diabetes susceptibility, particularly ND4 and tRNA Ala gene variants." (PMID 39835172, 2025). "Thus, T cell loss of Bcl6 prevents diabetes in VH125SD.NOD mice despite the expanded pool of anti-insulin B cells that reach the periphery." (PMID 40909612, 2025). "On the other hand, women might be more susceptible to the vascular effects of smoking and diabetes due to hormonal influences or differences in fat distribution and insulin sensitivity." (PMID 40756518, 2025). "Misfolding of INS can have detrimental consequences, leading to a diminished pool of functional INS, accumulation of misfolded INS within the ER, and subsequent ER stress implicated in β-cell apoptosis and the development of diabetes." (PMID 40052150, 2025). "This can be beneficial for managing blood sugar levels in people with diabetes hyperglycemia or elevated blood glucose concentration, which is a hallmark of diabetes, a chronic metabolic disease caused by an insufficient or malfunctioning insulin supply." (PMID 40143106, 2025). "Obesity, diabetes, and insulin-resistant states are generally associated with hypertriglyceridemia." (PMID 40943205, 2025). "Furthermore, berberine’s ability to lower glucose levels can interact with diabetes medications like insulin, sulfonylureas, or metformin, greatly increasing the risk of hypoglycemia." (PMID 40710568, 2025). "While some may resemble the severe insulin-deficient diabetes subgroup, our findings suggest broader enrichment across all T2D risk pathways." (PMID 40925988, 2025). "Additionally, the finding that non-insulin-treated diabetes was associated with a higher adjusted odds ratio for DCM than insulin-treated diabetes requires nuanced interpretation." (PMID 41153651, 2025). "Type 1 (T1D) and type 2 diabetes (T2D), the most common forms of diabetes, are characterized by the loss of functional pancreatic β-cells, which are responsible for the synthesis and release of insulin, the main hormone involved in the regulation of blood glucose levels." (PMID 39857806, 2025). "Its inverse association with HOMA-IR in advanced diabetes, observed in our study and supported by recent data, may reflect a paradoxical shift where visceral adiposity remains high but insulin secretion declines due to islet failure." (PMID 41465784, 2025). "The objective was to determine the association between serum IgE levels and the infiltration order of T lymphocytes and macrophages in pancreatic islets in relation to the loss of insulin and glucagon cells in presymptomatic congenic BB Gimap5-DP (Diabetes Prone) rats." (PMID 41042382, 2025).
diabetes (continued). "The explanations for these results may be as follows: first, excessive accumulation of visceral fat may adversely affect metabolic processes such as insulin sensitivity and inflammatory response, thereby increasing the risk of diabetes." (PMID 40190401, 2025). "While our data demonstrate impaired insulin sensitivity, low-dose GC treatment is associated with a lower incidence of diabetes in prospective studies, possibly due to reliance on fasting glucose measurements, which does not capture nuanced changes in glucose handlining and insulin sensitivity." (PMID 40622517, 2025). "Additionally, both treatment groups (metformin- and insulin-treated) exhibited comparable glycaemic control and comorbidity profiles, further reducing the risk of bias attributable to diabetes-related factors." (PMID 41285704, 2025). "However, future studies are needed to evaluate mechanisms underlying the formation of insulin-deficient islets in T1D and the role of α-cells in insulin secretion and diabetes pathogenesis." (PMID 39860066, 2025). "Glucose metabolism abnormalities, particularly diabetes, enhance liver fibrosis risk through oxidative stress pathway activation and chronic inflammatory response promotion, while disrupting hepatic gluconeogenesis and insulin metabolism." (PMID 40144884, 2025). "Bone-derived hormones are linked to insulin secretion, insulin resistance, and glucose metabolism, making them promising therapeutic targets for diabetes and its complications due to their potential effectiveness in maintaining glucose homeostasis and bone health." (PMID 39941397, 2025). "Also, REM sleep reduction due to induced sleep fragmentation has been linked to reduced insulin sensitivity, as well as increased consumption of carbohydrates and fat, which pose a greater risk for diabetes and obesity." (PMID 40817294, 2025). "Furthermore, they are consistent with prior research demonstrating that regular physical activity enhances glucose uptake, promotes insulin efficiency, and reduces the risk of diabetes-related complications." (PMID 41008487, 2025). "By mitigating oxidative stress, modulating metabolic signaling pathways, and protecting insulin-producing cells, K. pinnata may help reduce the progression of diabetes and its associated complications." (PMID 41155632, 2025). "Insulin users generally have more severe diabetes, which poses a higher risk." (PMID 40870519, 2025). "Moreover, booster COVID‐19 vaccines specifically weakened insulin sensitivity in patients with diabetes, providing a causal link between COVID‐19 vaccines and variations in insulin signaling." (PMID 41190280, 2025). "This study investigated changes in the risk of diabetes and the trajectory of β-cell function and insulin sensitivity during the pre-, peri-, and postmenopausal periods using longitudinal data collected over 16 years, considering the timing of incident diabetes and confounding variables." (PMID 40361840, 2025). "However, the positive associations of total SCFAs and propionate with diabetes risk remained unchanged among women after adjusting for these insulin measurements." (PMID 40078932, 2025). "Glucose-responsive insulin delivery systems that effectively regulate insulin retention and release in response to real-time fluctuation of glucose levels are highly desirable for diabetes care with minimized risk of hypoglycemia." (PMID 40807234, 2025). "This association was stronger among insulin-treated diabetes." (PMID 40810069, 2025). "The analysis demonstrated that patient knowledge and adherence to insulin administration practices are significantly associated with duration of diabetes, length of insulin therapy, and age, indicating that more experienced and older patients tend to have better insulin management skills." (PMID 41306599, 2025). "As a result they improve insulin sensitivity and may reduce the autoimmune responses linked with diabetes." (PMID 41459531, 2025).